PARK7 (Parkinsonism associated deglycase)
Diseases named in the same sentence as PARK7 in open-access papers (continued):
Sharing a sentence is not in itself a finding about the gene and the disease.
Parkinson disease (continued). "Proteins related to neurodegenerative disease were also found to be significantly changed in abundance, including proteins involved in Parkinson’s disease (PARK7) and amyotrophic lateral sclerosis (ubiquilin-4, superoxide dismutase, and RNA-binding protein FUS)." (PMID 34073856, 2021). "The downregulation of the PARK7/DJ-1 gene generated p-translucent (op) silkworms by reducing xanthine oxidase synthesis and elevating body oxidative stress response, which makes the p-translucent silkworm a good model to study Parkinson’s disease." (PMID 33614385, 2021). "PARK7 has been involved in some types of Parkinson ́s disease and other neurological disorders." (PMID 32157145, 2020). "Our previous research suggested that Parkinson’s disease family proteins, such as PARK15 and PARK7, are associated with tumorigenesis of non-small cell lung cancer, However, the Parkinson’s disease-associated proteins that are involved in the initiation of colon cancer have not yet been determined." (PMID 33308286, 2020). "If probes are simply ranked according to uncorrected p value, this co-localization enrichment increases to include 17 and 14 of the top-20 probes for the hypothalamus and eye, respectively, and includes additional transcripts of interest such as Dvl1 (Wnt signaling) and Park7 (Parkinson’s disease)." (PMID 32116548, 2020). "In addition, genetic studies have revealed that many causal genes of monogenic Parkinson’s disease, such as Parkin (PARK2), PINKl (PARK6), DJ-1 (PARK7), Omi/HtrA2 (PARK13), and CHCHD2 (PARK22), are associated with mitochondrial functions and quality control." (PMID 32937849, 2020). "Moreover, Nox-dependent ROS production occurs in Parkinson’s disease (autosomal recessive, early onset) 7 (Park7)-p47phox." (PMID 31412082, 2019). "Parkinson’s disease 7 (Park7) is autosomal recessive with an early onset and is a metabolic enzyme." (PMID 30770755, 2019). "Park2, Park7 and Pink1 stand out among Parkinson’s disease-specific genes downregulated by both treatments, since they are involved in biological processes characteristic of this disease, like dopamine uptake and neurotransmission, autophagy and degradation of mitochondria." (PMID 30382133, 2018). "Among the genes mutated in Parkinsonism, three autosomal inherited genes have been identified by Genome-Wide Association Studies to impact mitochondrial function: PARK2 (Parkin), PARK6 (PINK1), and PARK7 (DJ-1)." (PMID 29971063, 2018). "Park7(DJ-1)/Errfi1 locus is involved in Parkinson’s disease." (PMID 29387450, 2017). "Therefore, we focused our validation on two ASMs: Hcn2 with known roles in epilepsy, inflammatory and chronic pain, and Park7 (or DJ-1) for Parkinson’s disease." (PMID 29387450, 2017). "However, mutations in several genes have been shown to result in clinically typical autosomal dominant (SNCA, LRRK2, VPS35, DNAJC13) or recessive (PARK2, PINK1, PARK7) PD, or parkinsonism with atypical features (e.g. PARK9)." (PMID 26399558, 2015). "Genetic linkage studies of Parkinson's Disease (PD) have identified susceptibility loci in five genes which include SNCA (PARK1), Parkin (PARK2), PTEN-induced putative kinase (PINK1;PARK6), DJ-1 (PARK7) and Leucine rich repeat kinase 2 (LRRK2; PARK8)." (PMID 21812969, 2011). "Importantly, the finding of an association for both aSyn and PARK-7 in PDAC progression as revealed in this study suggests a possible nuance in the etiology of pancreatic cancer and Parkinson's disease that needs further interrogation." (PMID 21448452, 2011). "In addition to PARK6 (encoding PINK1) and PARK2 (encoding Parkin), other genes associated with Parkinson’s disease, such as PARK7 (encoding the DJ-1 protein) and PARK8 (encoding the LRRK2 protein), are also thought to be mutated in patients with Parkinson’s disease." (PMID 40463912, 2025).
Parkinson disease (continued). "Also this year, the following proteins were found to have implications for sporadic Parkinson's disease: PARK2 (encodes parkin), PINK1 (encodes PTEN-inducing putative kinase 1), PARK7 (encodes DJ-1), SNCA (encodes alpha-synuclein), LRRK2 (encodes dardarin), and HTRA2 (encodes Omi/HTRA2)." (PMID 38241161, 2024). "The expression of PARK7 is upregulated in various types of cancer, suggesting its potential role as a critical regulator of the pathogenesis of cancer and in the treatment of cancer and neurodegenerative diseases, including Parkinson’s disease, Alzheimer’s disease, and Huntington disease." (PMID 32357493, 2020). "Differentially expressed proteins such as PARK7 (DJ-1), VAMP2, and proteasome subunits are well-documented in the Parkinson’s disease literature, and their identification reinforces the biological plausibility of the observed alterations." (PMID 40725009, 2025). "According to another mechanism that relies on flotillins but not on their upregulation, Parkinson's disease‐associated DJ‐1/PARK7 deficiency is associated with flotillin 1 decrease and altered glutamate endocytosis that could exploit the role of flotillins as scaffolds of lipid raft domains." (PMID 39877933, 2025). "The absolute number of people with Parkinson’s disease who tested positive for PINK1, PARK7, VPS35 and SNCA was extremely low, precluding any detailed comments about genotype-phenotypes or participant characteristics for these groups." (PMID 39074992, 2024). "More than 30 loci are identified as risk factors for PD, some of which are extensively studied, such as mutations in genes encoding synuclein (SNCA), leucine-rich repeat kinase 2 (LRRK2), parkin (PRKN), and Parkinson disease protein 7 (PARK7)." (PMID 35805174, 2022). "DJ-1 (gene; PARK7) a recessively inherited Parkinson's gene, prevents oxidative stress in a Nrf2-dependent manner by preventing Keap1-mediated ubiquitination." (PMID 35126058, 2021). "The mutation of genes responsible for mitochondrial homeostasis can lead to familial forms of Parkinson’s disease: α-synuclein, parkin, phosphatase and tensin homolog-induced kinase 1 (PINK1), and Parkinson disease protein 7 (PARK7)." (PMID 33429934, 2021). "Recent genome-wide association studies have revealed the correlation of more than a dozen loci (including PARK1/4, PARK2, PARK5, PARK6, PARK7, PARK8, ATP13A2, PARK15, and GBA) with familial Parkinson’s disease." (PMID 33308286, 2020). "Our aim was to examine the possibility of using DJ-1 (PARK7), as a novel therapeutic target for Parkinson's disease." (PMID 26024237, 2015). "Alterations of SNCA, PARK2, PARK7, and PINK1 genes are involved in the early-onset Parkinson's disease (this is diagnosed before being 50 years old)." (PMID 26064418, 2015). "For example, DeepPFP failed to predict PARK7’s key BP term “cellular response to oxidative stress” (GO:0034599) in Parkinson’s disease, a mechanism that requires context-aware domain embeddings and GO hierarchy propagation." (PMID 41016015, 2025). "Subsequent chemoproteomic evaluation with 8RK64, an alkyne-bearing derivative of 8RK59, revealed enrichment of not only UCHL1 but also protein deglycase PARK7/DJ1, an attractive target in Parkinson’s disease with a similar molecular mass that overlaps with UCHL1 by gel analysis." (PMID 37111304, 2023). "DJ-1 protein, with encoding information on the PARK7 gene and a specificity for brain tissue, has several not clearly detected functions, mainly in Parkinson’s disease." (PMID 35207321, 2022). "As reported by a recent study, short stature and brachydactyly are two characteristics observed in parkinsonism patients without the PARK7 region in the DJ-1 gene." (PMID 35659283, 2022). "Interestingly, the deglycase activity of DJ-1, which is also known as Parkinson disease protein 7 (PARK7), plays an important role in the progression of a familial form of Parkinson’s disease." (PMID 32356279, 2020).
Parkinson disease (continued). "Leading examples include Parkin RBR E3 Ubiquitin Protein Ligase (PRKN), PTEN-induced kinase 1 (PINK1) and Parkinson disease protein 7 (PARK7), with robust evidence linking them to the development of PD." (PMID 39456761, 2024). "DJ-1, also known as Parkinson disease protein 7 (PARK7), plays an essential role in Parkinson disease (PD)." (PMID 34440621, 2021). "Several pathological mutations in the genes coding for PTEN-induced Kinase 1 (PINK1), Parkin, Leucine Rich Repeat Kinase 2 (LRRK2), glucocerebrosidase 1 (GBA1) and DJ-1 or PARK7 (Parkinson disease protein 7) were subsequently reported and established the genetic link to PD." (PMID 40540721, 2025). "PD-related genes have been discovered, for example, α-synuclein, Parkin, PINK1 (phosphatase and tensin homologue-induced putative kinase 1), LRRK2 (leucine-rich repeat kinase 2), and DJ-1 (also known as Parkinson disease protein 7 [PARK7])." (PMID 38841098, 2024). "Several genes, such as α-synuclein, parkin, PINK1 (phosphatase and tensin homologue-induced kinase 1), DJ1 (also known as Parkinson disease protein 7, PARK7 gene); and also environmental factors, like physical trauma, infections, and toxic effects have been identified to have a role in PD." (PMID 28216584, 2017). "Astrocyte-specific overexpression of human DJ-1 also known as Parkinson Disease Protein 7 (PARK7), a redox sensitive protein with multiple reported functions crucial for mitochondrial physiology and protein transcription, was shown to mitigate neurotoxicity in a PD rat model." (PMID 34531726, 2021). "First, we noticed that several well characterized causal genes for AD (APP, PSEN2 and SORL1), HD (HTT and SLC2A3), and Parkinson's disease (PD) (PARK2, PARK7) were bound by REST in hESCs but not mESCs." (PMID 25990720, 2015).
Parkinsonism (101 papers, 2004 to 2026). Characteristic neurologic anomaly resulting from degeneration of dopamine-generating cells in the substantia nigra, a region of the midbrain, characterized clinically by shaking, rigidity, slowness of movement and difficulty with walking and gait. "In PD, it was associated with Parkinsonism associated deglycase (DJ-1) and inflammatory responses induced by α-synuclein." (PMID 37008787, 2023). "PD caused by mutations in PARK2 has been suggested to have much in common with other early onset autosomal recessive forms of parkinsonism caused by mutations in PINK1/PARK6 or DJ-1/PARK7." (PMID 24115276, 2014). "Proteins identified as interactors of P301L but not WT tau included 14-3-3θ and DJ-1 (Parkinsonism-associated deglycase), a PD-related protein recently described as a P301L-specific tau interactor." (PMID 36634849, 2023).
neuroblastoma (48 papers, 2004 to 2025). Neuroblastoma (NB) is the most common solid, extracranial childhood tumor. "In addition, the knockdown of PARK7 in neuroblastoma cells resulted in a susceptibility to hydrogen peroxide-, MPP+-, and 6-OHDA-induced cell death." (PMID 33429934, 2021). "Additionally, knock-down of miR-34b/c in differentiated SH-SY5Y neuroblastoma cells resulted in a decrease in parkin and DJ-1 (encoded by PARK7) concentrations that led to a disturbance of mitochondria function and decrease in viability of the cell." (PMID 24797360, 2014). "For instance, 6-OHDA induces Park7 secretion via autophagy-based unconventional pathways in SH-SY5Y neuroblastoma cells and MEFs." (PMID 41353343, 2025). "To this end, we compared the PARK7/DJ-1 gene expression in SH-SY5Y neuroblastoma cells as a model for neuronal-like cells, and in HEK293 cells as a non-cancerous cell line." (PMID 39062793, 2024). "In vitro, Zerumbone can increase levels of PARK7, Nrf2 and HO-1, improve the viability of human neuroblastoma cells treated with 1-methyl-4-phenylpyridinium and reduce the ROS content and the number of apoptosis." (PMID 36408214, 2022). "The role of cellular homeostasis regulator cell cycle autoantigen (SG2NA) has also been demonstrated to increase the expression of PARK7/DJ-1 by inhibiting its proteasome-mediated degradation in Neuro2a neuroblastoma cells." (PMID 35743072, 2022). "PARK7 protects neuroblastoma cells from apoptosis induced by xanthoangelol-induced oxidative stress." (PMID 32357493, 2020). "Furthermore, the overexpression of miR-494 decreased the PARK7/DJ-1 level of adipocytes and neuroblastoma cells resulting in increased vulnerability of cells to oxidative stress." (PMID 35743072, 2022). "Interestingly, suppression of PARK7 expression in a neuroblastoma-based neuronal model also suppressed βIII-tubulin expression and microtubule dynamics, supporting the functional coupling of βIII-tubulin and PARK7." (PMID 35269398, 2022). "In addition to Stau2, DJ-1/Park7 has been experimentally demonstrated to coimmunoprecipitate with Sepw1 mRNA in M17 human neuroblastoma cells and human brain tissue." (PMID 24392277, 2013). "Upon KD of DJ-1 this regulatory mechanism is lost in neuroblastoma cells, suggesting that the lack of DJ-1 complexes may contribute to the increased susceptibility of DA and NOR neurons to neurodegeneration in PARK7-related PD." (PMID 29016861, 2017).
breast carcinoma (44 papers, 2006 to 2025). "With the increasing accessibility of multi-omics sequencing technologies, future studies are expected to validate the cross-ethnic consistency of the PARK7-breast cancer association in more diverse populations." (PMID 40657364, 2025). "This study provides novel insights into the causal role of oxidative stress (OS) in breast cancer (BC) development through an integrative multi-omics Mendelian randomization (MR) approach, identifying PARK7 as a key driver in BC pathogenesis." (PMID 40657364, 2025). "Existing research has predominantly focused on individual molecular levels, lacking an integrative analysis of multi-omics regulatory networks, which has hindered a comprehensive understanding of the complex associations between PARK7 and breast cancer (BC)." (PMID 40657364, 2025). "Serum PARK7 protein levels were further analyzed using enzyme-linked immunosorbent assay (ELISA) in both breast cancer patients and healthy controls." (PMID 40657364, 2025). "Among the 5 plasma proteins, SNUPN, CSK, and PARK7 emerged as “Strong” negatively causative associated proteins, indicating a protective effect against breast cancer development." (PMID 38304232, 2023). "Overall, we found 5 proteins (PEX14, CTSF, SNUPN, CSK, PARK7) with strong causal links to breast cancer." (PMID 38304232, 2023). "However, further experimental studies are needed to clarify the directionality of the associations between PARK7 and breast cancer." (PMID 39351539, 2024). "In summary, the relationship between PARK7 and breast cancer risk remains inconclusive." (PMID 39351539, 2024). "In breast cancer, low PARK7 expression was correlated with pathological complete response in 79.6% of cases following neoadjuvant therapy, and loss of PARK7 function is associated with increased sensitivity to doxorubicin in breast cancer cells." (PMID 38304232, 2023). "Moreover, the loss of function of ERBB3 reduces the serum levels of PARK7 in breast cancer cells." (PMID 32357493, 2020). "The results demonstrated that the mRNA levels of PARK7 in plasma from breast cancer patients were significantly lower than those in the healthy control group." (PMID 40657364, 2025). "Decreased levels of CASP8, DDX58, CPNE1, ULK3, PARK7, and BTN2A1, as well as increased levels of TNFRSF9, TNXB, DNPH1, and TLR1, were linked to an elevated risk of breast cancer." (PMID 39351539, 2024). "PARK7 is supported by secondary evidence strength in our study, suggesting its potential as a therapeutic target for breast cancer." (PMID 39351539, 2024). "PARK7 also enhances the metastatic ability of breast cancer and MM by inducing epithelial–mesenchymal transition via suppression of the expression of Krűppel-like transcription factor (KLF) 17 and KLF6." (PMID 32357493, 2020). "PARK7 has been detected in the cytoplasm of invasive breast cancer cells and is highly expressed in 79% of patients with breast cancer." (PMID 32357493, 2020). "The expression of PARK7 is significantly correlated with high rates of complete pathological remission following chemotherapy with trastuzumab in patients with breast cancer." (PMID 32357493, 2020). "Highly metastatic breast cancer cells show increased expression of PARK7 and low expression of retained PARK7." (PMID 32357493, 2020). "The loss of function of PARK7 increases adriamycin sensitivity and reduces the activation of AKT in breast cancer cells." (PMID 32357493, 2020). "We observed a marked reduction in PARK7 protein levels in breast cancer patients." (PMID 40657364, 2025). "The remaining 3 proteins, SNUPN (OR = 0.905, p < 0.001), CSK (OR = 0.962, p = 0.038), and PARK7 (OR = 0.954, p < 0.001), all exhibited negative causations with breast cancer." (PMID 38304232, 2023). "An increase in the expression of secretory PARK7 in invasive ductal carcinomas may explain its involvement in the pathogenesis of this type of breast cancer." (PMID 32357493, 2020).
breast carcinoma (continued). "In addition, secreted PARK7 is highly expressed in the serum and nipple fluid of patients with breast cancer and is involved in the regulation of RNA–protein interactions." (PMID 32357493, 2020). "However, the activation of ERBB3 mediated by NRG1 reduces the interaction of ERBB3 with PARK7 in breast cancer cells." (PMID 32357493, 2020). "Moreover, several Tip60-targeted Khib were identified on cancer biomarkers, such as plectin (PLEC, related to ovarian cancer), alcohol dehydrogenase class-3 (ADH5, related to breast cancer), and PARK7 (related to lung cancer), which therefore links Tip60 and the Khib pathway to cancer." (PMID 35178156, 2022). "Moreover, high expression of PARK7 in breast cancer potentiates HER3 signaling and therefore may serve as a target for molecular therapies." (PMID 28686225, 2017). "CASP8, DDX58, CPNE1, ULK3, PARK7, and TNFRSF9 have already been identified as targets in drug development and potential therapeutic targets for breast cancer treatment." (PMID 39351539, 2024). "Treatment with paclitaxel inhibits the proliferation and metastatic potential of breast cancer cells by inducing the expression of KLF17 and suppressing the expression of snail, PARK7, and ID1, which results in the inhibition of epithelial-mesenchymal transition." (PMID 32357493, 2020). "DJ-1/PARK7 (Parkinson Protein 7) is a novel interaction partner of HER3 and high DJ-1 expression in breast cancer cells predicts elevated HER3 signaling and may therefore serve as a biomarker for HER3 targeted antibody cancer therapies." (PMID 28036286, 2017). "Using a proteomic approach, we could show that several antioxidant proteins, for example, SOD1, PRDX2, and PARK7, were downregulated in the normo-sensitive patients and some antioxidant proteins, for example, BLVRB and PRDX2, were upregulated in the radiosensitive breast cancer patients." (PMID 29951164, 2018).